HLA-DQA2 (major histocompatibility complex, class II, DQ alpha 2)
Description:
Binds peptides derived from antigens that access the endocytic route of antigen presenting cells (APC) and presents them on the cell surface for recognition by the CD4 T-cells. The peptide binding cleft accommodates peptides of 10-30 residues. The peptides presented by MHC class II molecules are generated mostly by degradation of proteins that access the endocytic route, where they are processed by lysosomal proteases and other hydrolases. Exogenous antigens that have been endocytosed by the APC are thus readily available for presentation via MHC II molecules, and for this reason this antigen presentation pathway is usually referred to as exogenous. As membrane proteins on their way to degradation in lysosomes as part of their normal turn-over are also contained in the endosomal/lysosomal compartments, exogenous antigens must compete with those derived from endogenous components. Autophagy is also a source of endogenous peptides, autophagosomes constitutively fuse with MHC class II loading compartments. In addition to APCs, other cells of the gastrointestinal tract, such as epithelial cells, express MHC class II molecules and CD74 and act as APCs, which is an unusual trait of the GI tract. To produce a MHC class II molecule that presents an antigen, three MHC class II molecules (heterodimers of an alpha and a beta chain) associate with a CD74 trimer in the ER to form a heterononamer. Soon after the entry of this complex into the endosomal/lysosomal system where antigen processing occurs, CD74 undergoes a sequential degradation by various proteases, including CTSS and CTSL, leaving a small fragment termed CLIP (class-II-associated invariant chain peptide). The removal of CLIP is facilitated by HLA-DM via direct binding to the alpha-beta-CLIP complex so that CLIP is released. HLA-DM stabilizes MHC class II molecules until primary high affinity antigenic peptides are bound. The MHC II molecule bound to a peptide is then transported to the cell membrane surface. In B-cells, the interaction between HLA-DM and MHC class II molecules is regulated by HLA-DO. Primary dendritic cells (DCs) also to express HLA-DO. Lysosomal microenvironment has been implicated in the regulation of antigen loading into MHC II molecules, increased acidification produces increased proteolysis and efficient peptide loading.
Synonyms: HLA-DXA; DC-alpha; DQA1; DX-ALPHA; HLA-DCA; HLADQA2
Tractability: Antibody: UniProt places it where antibodies can reach, with high confidence; its Gene Ontology location is reachable by antibodies, with high confidence; UniProt predicts a signal peptide or a membrane-spanning region. PROTAC: ubiquitination databases record sites on it.
Gene: Protein-coding gene on chromosome 6 (32,741,391 to 32,747,198, forward strand). Ensembl gene ENSG00000237541.
Subcellular location: Cell membrane; Endoplasmic reticulum membrane; Golgi apparatus, trans-Golgi network membrane; Endosome membrane; Lysosome membrane
Pathways (Reactome):
Immune System: Co-inhibition by PD-1; Downstream TCR signaling; Generation of second messenger molecules; Interferon gamma signaling; MHC class II antigen presentation; Phosphorylation of CD3 and TCR zeta chains; Translocation of ZAP-70 to Immunological synapse
Gene Ontology:
Molecular function: protein binding; MHC class II protein complex binding; MHC class II receptor activity; peptide antigen binding
Biological process: antigen processing and presentation of exogenous peptide antigen via MHC class II; immune response; peptide antigen assembly with MHC class II protein complex; positive regulation of immune response; positive regulation of T cell activation; antigen processing and presentation
Cellular component: clathrin-coated endocytic vesicle membrane; endocytic vesicle membrane; ER to Golgi transport vesicle membrane; Golgi membrane; late endosome membrane; lumenal side of endoplasmic reticulum membrane; lysosomal membrane; MHC class II protein complex; plasma membrane; trans-Golgi network membrane; transport vesicle membrane; endoplasmic reticulum membrane; endosome membrane; Golgi apparatus; membrane
Genetic constraint (gnomAD): Loss-of-function variants: 17 observed, 20.02 expected, observed/expected ratio (o/e) 0.85, 90% interval 0.58 to 1.27. The upper end of that interval is the gene's LOEUF score, 1.27, which puts it in group 5 of 6, group 1 being the genes least tolerant of losing a copy. Missense variants: 239 observed, 291.61 expected, observed/expected ratio (o/e) 0.82, 90% interval 0.74 to 0.91. Synonymous variants: 81 observed, 103.59 expected, observed/expected ratio (o/e) 0.78, 90% interval 0.65 to 0.94.
Homologues: Orthologues: chimpanzee HLA-DQA2 (98% identical), tropical clawed frog mhc2-daa (44% identical), zebrafish mhc2daa (27% identical), zebrafish si:busm1-194e12.8 (26% identical), zebrafish mhc2d8.35a1 (25% identical), zebrafish mhc2d8.37a2 (24% identical), zebrafish mhc2d8.46a (24% identical), zebrafish mhc2dga (24% identical), zebrafish mhc2d8.37a1 (23% identical), zebrafish zgc:123107 (22% identical), zebrafish zmp:0000001006 (17% identical), zebrafish mhc2dca (15% identical). Paralogues in human: HLA-DQA1 (89% identical), HLA-DPA1 (55% identical), HLA-DOA (54% identical), HLA-DRA (52% identical), HLA-DMA (25% identical), HLA-DRB1 (23% identical), HLA-DOB (22% identical), HLA-DMB (22% identical), HLA-DQB2 (22% identical), HLA-DRB5 (22% identical), HLA-DQB1 (21% identical), HLA-DPB1 (20% identical), and 1 more.